GMPS (guanosine monophosphate synthase)
Diseases named in the same sentence as GMPS in open-access papers:
GMPS is named in the same sentence as 33 diseases in open-access papers, as found by Europe PMC text mining. Sharing a sentence is not in itself a finding about the gene and the disease. The quoted sentences say what the papers report.
liver cancer (7 papers, 2017 to 2025). An epithelial or non-epithelial malignant neoplasm that arises from the liver. "Among emerging molecular candidates, the epigenetic writer DNMT3A and the metabolic enzyme GMPS have attracted attention for their potential prognostic significance in liver cancer." (PMID 41465346, 2025). "In this context, the present study aims to further explore DNMT3A and GMPS as prognostic and potentially predictive biomarkers in liver cancer and pancreatic cancer, with the goal of clarifying their biological roles and translational utility." (PMID 41465346, 2025). "Knockdown of GMPS has been shown to reduce cell proliferation and promote cellular senescence and apoptosis in cervical and liver cancer, underscoring its importance in cancer biology." (PMID 39822281, 2025). "For lung cancer, GMPS, EPHA10, C10orf54, and MAGEA6 are highly expressed in different subtypes; for liver cancer, CMYA5, DEPDC6, FAU, VPS24, RCBTB2, LOC100133469, and SLC35B4 are significantly expressed in different subtypes." (PMID 33747053, 2021).
breast carcinoma (5 papers, 2017 to 2025). "All survival data for survival analysis were collected for breast cancer patients, available at cbioportal.org, with protein expression data for GMPS and DNMT3A." (PMID 41465346, 2025). "GMPS, which catalyzes the final steps of the de novo nucleotide synthesis pathway, resulting in GMP production, was shown to be required to sustain an invasive phenotype of breast carcinoma in our in vitro and mouse xenograft experiments." (PMID 29257071, 2017).
melanoma (5 papers, 2020 to 2025). A malignant, usually aggressive tumor composed of atypical, neoplastic melanocytes. "In human melanoma samples, increased GMPS protein expression was found in metastatic lesions compared to localized tumors, and the pharmacological inhibition of GMPS decreased melanoma cell proliferation and invasion, both in vitro and in vivo." (PMID 33224873, 2020). "GMPS inhibitor could also potentially modulate melanoma cell invasion in vitro." (PMID 34035425, 2021). "Moreover, RT‒PCR analysis revealed that the abundance of key enzymes involved in purine nucleotide metabolism, such as adenyl succinate lyase (ADSL), IMP dehydrogenase 1/2 (IMPD1/2), and GMP synthase (GMPS), was significantly decreased in NDUFS3-knockdown melanoma cells." (PMID 40404919, 2025).
glioblastoma (3 papers, 2017 to 2021). The most malignant astrocytic tumor (WHO grade IV). "Elevated expression of purine synthetic enzymes (PRPS1, ADSL, and GMPS) in metabolic subpathway 00230_5/00230_6 of the purine metabolic pathway is correlated with poor prognosis in glioblastoma patients." (PMID 33072547, 2020). "Importantly, shRNA knockdown of the purine synthesis enzymes PRPS1 (phosphoribosyl pyrophosphate synthetase 1), ADSL (adenylosuccinate synthase), or GMPS strongly suppressed the development of glioblastoma tumors in immunocompromised mice." (PMID 29257071, 2017). "However, in this glioblastoma study, the observation that GMPS knockdown prevents tumor growth supports the notion that GMPS may contribute to the establishment of the metastatic niche via crosstalk with neighboring cells." (PMID 29257071, 2017).
Pancreatic Cancer (3 papers, 2021 to 2025). "DNMT3A and GMPS have also been implicated in pancreatic tumor biology, motivating a cross-tumor investigation." (PMID 41465346, 2025). "Collectively, these findings position DNMT3A and GMPS as context-dependent biomarkers that integrate metabolic and immune cues to shape prognosis in liver and pancreatic cancer, offering mechanistic insight and translational relevance for patient stratification." (PMID 41465346, 2025). "Thus, GMPS overexpression significantly enhances the proliferation and migration ability of pancreatic cancer cells in vitro." (PMID 34930261, 2021).
prostate carcinoma (3 papers, 2021 to 2022). A carcinoma that arises from epithelial cells of the prostate gland. "A recent report showed that the inhibition of GMPS could block glutamine metabolism and the growth of prostate cancer." (PMID 35957801, 2022).
diabetes (2 papers, 2020 to 2021). "The regulation of diabetes is caused by genes including ASNS, CAD, GMPS, and PHGDH." (PMID 33490239, 2020).
neuroblastoma (2 papers, 2021 to 2022). Neuroblastoma (NB) is the most common solid, extracranial childhood tumor. "All these reactions in purine and pyrimidine nucleotide synthesis are catalyzed by glutamine amidotransferases (PPAT, PFAS, GMPS, CAD, and CTPS1/2), which are transcriptionally activated by MYCN in neuroblastoma cells." (PMID 36077650, 2022).
ovarian carcinoma (2 papers, 2019 to 2021). A malignant neoplasm originating from the surface ovarian epithelium. "Specifically, GMPS was highly expressed in ovary cancer tissues, which was associated with RFS, whereas the expression of PR, CD40, and p21 mRNA was reduced in ovarian cancer tissues, which was associated with poor RFS." (PMID 30701134, 2019). "In conclusion, this study profiled differentially expressed genes using the ovarian cancer progression model and identified four (i.e., GMPS, PR, CD40, and p21) as prognostic markers for ovarian cancer patients." (PMID 30701134, 2019). "The bioinformatic data revealed four genes (i.e., guanosine 5′-monophosphate synthase (GMPS), progesterone receptor (PR), CD40, and p21 (cyclin-dependent kinase inhibitor 1A)) to play an important role in ovarian cancer progression." (PMID 30701134, 2019). "In our current study, we found that GMPS was highly expressed in ovary cancer tissues compared with that of non-tumor tissues and that GMPS expression was associated with RFS of patients." (PMID 30701134, 2019).
brain tumor (1 paper, 2020). "The knockdown of ADSL, GMPS, and PRPS1 decreases brain tumor initiating cell maintenance in both immunodeficient and immunocompetent mouse models." (PMID 32218208, 2020).
esophageal cancer (1 paper, 2021). A primary or metastatic malignant neoplasm involving the esophagus. "Altogether, we concluded that the increase in RCF4 and GMPS may be mediated by DNA copy number alterations, and that the increased expression of RFC4 and GMPS was associated with an early tumor stage and early nodal metastatic status in esophageal carcinoma." (PMID 34520390, 2021). "The results indicated that the expression of RFC4 was highly correlated with the expression of GMPS in esophageal carcinoma in TCGA data." (PMID 34520390, 2021). "Among the most significant DEGs, RFC4 and GMPS were both increased in the early stage and early nodal metastases of esophageal carcinoma." (PMID 34520390, 2021). "In order to further explore the expression of RFC4 and GMPS in the esophageal carcinoma, the Oncomine dataset was used." (PMID 34520390, 2021). "The function of RFC4 and GMPS in esophageal cancer were highly consistent." (PMID 34520390, 2021). "In future, RFC4 and GMPS may serve as the targets for immunotherapy of esophageal cancer and improve the treatment of esophageal cancer." (PMID 34520390, 2021). "Therefore, we reasonably concluded that RFC4 and GMPS involved in the immune regulation of esophageal cancer." (PMID 34520390, 2021). "Furthermore, the discovery of RFC4 and GMPS can help us better understand the early diagnosis and treatment of esophageal cancer." (PMID 34520390, 2021). "Therefore, we investigated the relationship between RFC4 and GMPS expression and immune infiltration in esophageal carcinoma using the online tool TIMER." (PMID 34520390, 2021). "In summary, we speculate that RFC4 and GMPS overexpression might influence tumor immune responses in the tumor microenvironment and that they may play a crucial role in esophageal carcinoma progression." (PMID 34520390, 2021). "Therefore, we inferred that DNA copy number alterations mediated the increase in RFC4 and GMPS in the early stage of esophageal carcinoma." (PMID 34520390, 2021). "Furthermore, RFC4 and GMPS were both upregulated in the early stage and early nodal metastases of esophageal carcinoma." (PMID 34520390, 2021). "Therefore, we hypothesize that RFC4 and GMPS are involved in the early progression of esophageal cancer, and mediate the immune escape of esophageal carcinoma." (PMID 34520390, 2021). "A high expression of RFC4 and GMPS could mediate immune escape from esophageal cancer." (PMID 34520390, 2021). "Therefore, we inferred that the levels of RFC4 and GMPS may be mediated by an increased DNA copy number and related to the occurrence of esophageal cancer." (PMID 34520390, 2021). "Finally, we concluded that RFC4 and GMPS are significant for the early diagnosis of esophageal carcinoma and that they may participate in the tumor immune response." (PMID 34520390, 2021). "To further explore the reason for the increased RFC4 and GMPS in ESCC, we first explored genetic alterations in RFC4 and GMPS in esophageal carcinoma by a cBioPortal analysis." (PMID 34520390, 2021). "In addition, RFC4 and GMPS perform the similar functions, and the expression of RFC4 was highly correlated with the expression of GMPS in esophageal cancer." (PMID 34520390, 2021).
glioma (1 paper, 2021). A benign or malignant brain and spinal cord tumor that arises from glial cells (astrocytes, oligodendrocytes, ependymal cells). "The gene expression levels of H6PD, G6PD, ADSL, APRT, GMPS, PRPS1, and IMPDH1 in human glioma patients were significantly higher than those in the control group." (PMID 33723244, 2021).
metabolic syndrome (1 paper, 2022). A cluster of metabolic risk factors for CARDIOVASCULAR DISEASES and TYPE 2 DIABETES MELLITUS. "It was shown that the metabolic syndrome-related gene guanosine monophosphate synthetase (GMPS) could predict prognosis in pancreatic ductal adenocarcinoma (PDAC)." (PMID 36530401, 2022).
mucinous tumors (1 paper, 2012). "These include: FH, GMPS, PIK3CA, EIF4A2, ZNF384, and SS18L1 (amplifications in serous tumors); TET2, FGFR10P, NF1, ERBB2, and SH3GL1 (deletions in serous tumors) and ERBB2 (amplifications in mucinous tumors)." (PMID 23078675, 2012).
tongue cancer (1 paper, 2019). A malignant neoplasm affecting the tongue. "Assessment of ECS, an additional prognosticator in advanced stage disease, indicated a distinct set of markers in tongue cancer (EXT1, GMPS, TSTA3), while in laryngopharyngeal cancers a majority of the markers were common those associated with late stage disease." (PMID 31310629, 2019).
cancer (17 papers, 2012 to 2025). A tumor composed of atypical neoplastic, often pleomorphic cells that invade other tissues. "GMPS was reported to be up-regulated in various malignant tumors, such as lung squamous cell carcinoma, ovarian serous cystadenocarcinoma and head and neck squamous cell carcinoma." (PMID 39189649, 2024). "In cancer, the upregulation of guanosine monophosphate synthase has been described and related to apoptosis inhibition and chemoresistance." (PMID 38247476, 2023). "By conducting an online TCGA analysis, we found that the expression of RFC4 and GMPS was upregulated in many cancers." (PMID 34520390, 2021). "The Cancer Genome Atlas (TCGA) dataset showed upregulated GMPS expression in various cancers, including NPC." (PMID 32005234, 2020). "GMPS regulates chromatin dynamics and is overexpressed in several cancers." (PMID 41257548, 2025). "So far, there has not been much research on GMPS as a drug target, and future research will give us more insight into what role this crucial enzyme at the last step of GMP synthesis plays in cancer." (PMID 39189649, 2024). "Targeting of GMPS, CKS1B, and RAD21 by 2 individual siRNAs attenuated colony-formation potential of cancer cells, while depletion of RAD54L failed to exhibit any effect on colony formation." (PMID 36201246, 2022).
tumor (17 papers, 2017 to 2026). "We uncovered that a high expression of RFC4 and GMPS accompanied by high levels of tumor-infiltrating immune cells was associated with a poor prognosis." (PMID 34520390, 2021). "GMPS (GMP synthase), the rate-limiting enzyme in de novo purine synthesis, has a high expression level associated with tumor-cell proliferation and chemoresistance." (PMID 40236698, 2025). "On spatial sections, the expression of GMPS was diffusely distributed within the tumor area, and the population with high GMPS expression typically demonstrated a poorer response to immunotherapy." (PMID 40236698, 2025). "Compared to the paired normal tissues, the results showed that RFC4 and GMPS were upregulated in the ESCC tumor tissues." (PMID 34520390, 2021). "Taken together, these findings indicate that DNMT3A and GMPS exert context-dependent effects that are closely linked to the TME and immunogenomic landscape of each tumor type, emphasizing their potential as biomarkers for patient stratification and precision immuno-metabolic therapies." (PMID 41465346, 2025). "DNMT3A and GMPS are overexpressed in tumor versus normal tissues of HCC and PDAC." (PMID 41465346, 2025). "Moreover, knockdown of GMPS in PDAC cells suppressed proliferation, migration, and invasion of tumor cells, whereas overexpression of GMPS performed oppositely." (PMID 34930261, 2021). "However, a low expression of RFC4 and GMPS with a high expression of some tumor-infiltrating immune cells showed a good prognosis." (PMID 34520390, 2021). "Moreover, to further investigate the association between the expression levels of RFC4 and GMPS and the clinicopathological features in ESCC, we divided the 46 tumor samples into two groups according to the cutoff values (median of RFC4, mean of GMPS) of RFC4 and GMPS mRNA expression levels." (PMID 34520390, 2021). "Thus, the downregulation of miR-99a may inhibit tumor proliferation by upregulating GMPS, but it still requires experimental validation." (PMID 33274225, 2020). "The impact of tumor environment was evaluated in the same patient population against the expression of DNMT3A and GMPS." (PMID 41465346, 2025). "The impact of the tumor environment was evaluated in the same patient population against the expression of DNMT3A and GMPS." (PMID 41465346, 2025). "The observed divergence in the prognostic impact of DNMT3A and GMPS between PDAC and HCC underscores the importance of tumor-specific immune and metabolic contexts in shaping clinical outcomes." (PMID 41465346, 2025). "Further RRM2, GMPS, BCAT1, PYCR2, and NEU1 are identified in tumor tissue as actionable candidates for prevention." (PMID 40290517, 2025). "According to our analyses, ADM exhibited positive correlation with metabolic reprogramming, particularly in purine (PPAT, GMPS, RRM1, and RRM2) and pyrimidine (CAD and UMPS) metabolic pathways, suggested that it played an important role in tumor cell metabolic adaptation." (PMID 40547013, 2025). "In tumor tissue, these pathways were significantly deregulated regarding gene and protein expression in two independent datasets, including actionable targets RRM2, GMPS, BCAT1, PYCR2, and NEU1." (PMID 40290517, 2025). "Among the candidate biomarkers, the DNA methyltransferase DNMT3A and the guanine monophosphate synthetase (GMPS) have emerged as potential prognostic drivers, yet their roles across tumor contexts remain unclear." (PMID 41465346, 2025). "Therefore, we measured the expression levels of RFC4 and GMPS in 46 pairs of ESCC tumor samples and adjacent normal tissues to prove RFC4 and GMPS were increased in ESCC." (PMID 34520390, 2021). "In summary, our study shows that RFC4 and GMPS have potential as biomarkers for the early diagnosis of ESCC and may played a crucial role in the process of tumor immunity in ESCC." (PMID 34520390, 2021).
tumor (continued). "Through a tumor-infiltrating immune analysis, we found that RFC4 and GMPS were correlated with some tumor-infiltrating immune cells and that an increased expression of RFC4 and GMPS could result in a poor prognosis." (PMID 34520390, 2021).
infection (5 papers, 2018 to 2023). The state of being infected such as from the introduction of a foreign agent such as serum, vaccine, antigenic substance or organism. "The inhibition of GMPS activity can reduce the ability of pathogen infection." (PMID 34203217, 2021). "Whereas the functions of gammaherpesvirus GMPs have been extensively investigated for EBV and KSHV in cell culture in vitro, animal gammaherpesviruses have provided important insights on the role of GMPs during in vivo infection." (PMID 30687291, 2018). "Indeed, GMPS knock-out cell line was not able to produce infection in mice and specific GMPS inhibitors arrested the parasite ́s growth in vitro." (PMID 29481567, 2018).
GMPS also shares sentences with these, for which no sentence is quoted: leukemia (2 papers); lung carcinoma (2); nasopharyngeal carcinoma (2); Arthritis (1); Chagas disease (1); Colon Cancer (1); COVID-19 (1); endometrial cancer (1); hepatocellular carcinoma (1); metastatic cancer (1); metastatic melanoma (1); metastatic tumor (1); pancreatic ductal adenocarcinoma (1); synovial sarcoma (1); triple-negative breast carcinoma (1).